CD4 (CD4 molecule)
Diseases named in the same sentence as CD4 in open-access papers (continued):
Sharing a sentence is not in itself a finding about the gene and the disease.
infection (continued). "In the current study, we characterized the population of CD4+ and CD8+ DP T cells according to their PD‐1 and Tim‐3 expression phenotype and specificity to HCV NS3 epitope in patients with chronic HCV infection and in patients who spontaneously cleared the infection." (PMID 30972915, 2019). "Moreover, regardless of the frequency of infection, cell-associated HIV-1 DNA measured by qPCR was more abundant in CD4+/− TRM with a median of 4.4 vDNA molecules/cell compared to 0.43 in non-TRM (p = 0.016)." (PMID 31628331, 2019). "However, fTr±QA booster did not enhance the DNA vaccine induced CD4+T cell responses after challenge infection." (PMID 31293599, 2019). "Although there were no statistically significant trends between infection groups for CD4+ T lymphocytes, CD8+ T lymphocytes, γδ T lymphocytes, or CD14+ monocytes, the mean change in percentages of CD4+ T lymphocytes appeared to be higher in control animals when compared with infected animals." (PMID 31470560, 2019). "Conversely, CD4+ T cells do not express Fas after infection, and have increased IFN-γ production." (PMID 31608052, 2019). "However, despite the abundance of evidence for the role of CD4 and CD8 T cells in protection against influenza infection in mice and humans, there are few studies in pigs analyzing in depth T cell immunity in response to immunization or infection." (PMID 30804933, 2019). "The goal of this study was to investigate whether the highly proliferative memory SAMHD1low CD4+ T cells, previously identified by our group as being permissive to HIV-1 and significantly depleted during infection, contribute to HIV-1 persistence by potentially replenishing the reservoir." (PMID 31220191, 2019). "CD127+CD4+ T cells also exhibited increased rates of apoptosis in untreated infection relative to healthy controls suggesting in untreated infection, CD127 expression on memory cells is not itself sufficient to maintain cell survival in the face of uncontrolled HIV-1 viremia." (PMID 31507594, 2019). "With adjusting for other helminths in our multivariate analysis, we clearly showed that the described CD4 T cell activation in W. bancrofti- (but also in A. lumbricoides and T. trichiura) -infected individuals was independent of concomitant infection with other helminths." (PMID 31425508, 2019). "Detailed clinical data was collected and plasma viral load and CD4+T cell counts measured longitudinally starting from the time of HIV-1 diagnosis (median of 44 days post estimated date of infection) and continuing at 3-month intervals thereafter up to 6 years post infection." (PMID 31449552, 2019). "Consequently, in this study we generated CD4+ T cell-specific IL-4Rα−/− (LckcreIL-4Rα−/lox) mice and iLckcreIL-4Rα−/lox mice that lack IL-4Rα on both CD4 and CD8 T cells to determine the temporal role of IL-4 signaling via CD4+ and CD8+ T cells on the progression of VL infection." (PMID 31475014, 2019). "Given the results above and observations that NK cells can maximize neutrophil responses in vivo, we next depleted NK cells in naïve mice receiving WT memory CD4 T cell prior to IAV challenge to determine whether and how NK cells impact the outcome of infection." (PMID 31412088, 2019). "Needle-free SL/B and ID/SC immunization both results in a significant delay in acquisition of infection compared to unvaccinated controls, with non-neutralizing antibody effector functionality and Env-specific CD4 T-cell responses being the predominant correlates of protection." (PMID 30778066, 2019). "Analysis of CD4+ T cell subsets revealed an increase in TFH cells and IFNγ-, IFNγ+ TNF+-, and IL-2-producing CD4+ T cells and a decrease in Treg cells in Mock-immune compared with ZIKV-immune mice, which is consistent with the observation that Treg cell number peaks at day 3 after primary infection." (PMID 30677097, 2019).
infection (continued). "In addition to CD4+ Th1 as the principle source of IFN-γ, CD8+ T cells also contribute to IFN-γ secretion in M. tuberculosis, Chlamydia, L. monocytogenes, Rickettsia, and F. tularensis infections." (PMID 31111075, 2019). "Finally, in the i.d. infection model, B cells appear to be indispensable, like in the i.p. model, but CD4+T cells are required in the lesion but not in the spleen." (PMID 31354728, 2019). "(C–F) RhIV viremia (log10 RNA copies/ml of plasma, upper rows) and blood CD4+ T-cell proportion (% of CD3+ cells, lower rows) in A1Ifnar-/- mice (C), A1Ifnar-/-, C18Ifnar-/-, and B4Ifnar-/- mice (D, F) or A1Ifnar+/+ mice (E) at the indicated times following infection with the indicated RhIV strains." (PMID 31644426, 2019). "CD4+ T cell frequencies in both statin-treated cohorts were similar to SIV/Untreated controls, except in SIV/Statin Group 2 at 1 and 3 weeks post-infection; however, cell numbers recovered by 8 weeks post-infection and remained similar throughout the remainder of the experiment." (PMID 31882598, 2019). "Though there were no major changes in the proportions of CD4 T cells or its subsets, central memory CD4 T cells from female macaques were found to differentially regulate a significantly larger number of genes at day 4 post-infection (PI) as compared to males." (PMID 31490965, 2019). "Whereas the overall frequencies of pulmonary CD4+ T cells were not measurably affected by gastric H. pylori infection irrespective of the age at the time of infection, we detected shifts in pulmonary Treg frequencies that were consistent with those observed in the gastric LP." (PMID 30890606, 2019). "As expected, the results showed that HIVgp(T)-VLPs can efficiently infect and produced high Gluc activity in CD4+ C8166 T cells, while HIVgp(M)-VLPs and HIVgp(M)/EboGP-VLPs infection did not produce significant levels of Gluc activity as compared to negative control (Gag-VLP)." (PMID 31100082, 2019). "Furthermore, mucosal CD4+ T cells expressed higher levels of transcripts for IL-21R as compared with other immune and non-immune cells after infection with C. rodentium." (PMID 30818341, 2019). "Together, these findings suggest that Foxp3+ Tregs, like effector CD4+ T cell subsets, respond to local cytokines by modifying their chemokine receptors including CXCR3 to promote their migration to sites of inflammation and infection where they function to suppress immune responses." (PMID 30915078, 2019). "Even if the dendritic cells were not killed, CD4+ T cell engagement might deliver anti-viral signals and arrest their migration, thereby reducing their capacity to spread infection." (PMID 29447285, 2018). "The nature of the APC that are involved in initial of priming CD4 T cells in responses to infection or vaccination is not well understood, but may involve multiple subsets contacted sequentially." (PMID 29681900, 2018). "Therefore, the evidence suggests the presence of an important link between the sensing of initial tissue damage by platelets in the absence of infection and the proliferation and differentiation of CD4 T cells at the site of injury." (PMID 29599771, 2018). "We therefore raised the question of whether MIF-treated MDM-derived supernatants could promote the infection of unactivated primary CD4+ T-cells in the absence of other stimuli." (PMID 29997630, 2018). "Although sequential infection and sequential WIV immunization induced virus-specific IFNγ-producing CD4 T cells, depletion of CD4 T cells in this study did not influence the cross-protection, neither in the sequential infection group nor in the sequential WIV vaccination group." (PMID 30356772, 2018). "In addition, the infiltration of Gr-1+CD45+ cells and the overall numbers of CD45+ cells, including CD4+ and CD8+ T cells, into the CNS was significantly lower in mice treated with anti-KC antibody compared to the control mice at early infection and during disease onset." (PMID 29410948, 2018).
infection (continued). "Similarly, the absence of OX40 does not affect the expression of CXCR5 on antigen-specific CD4+ T cells and the development of IgG1 responses after infection with the rodent roundworm Heligmosomoides polygyrus." (PMID 30405612, 2018). "Furthermore, differences in CD4 and CCR5 expression levels can affect the CCR5-mediated infection of macrophages, resulting in a shift in cell tropism that is similar to what is observed during FIV infection." (PMID 29677122, 2018). "Thus, regardless of the method of phenotyping CD4+ T cells, aged mice do not have the same T cell subset differentiation and distribution as young mice following infection." (PMID 29616390, 2018). "In fact, the depletion of effector CD4+ T cells in murine models did not appear to influence resistance to infection, while the depletion of CD8+ T effector cells reversed the protective effect, which led to a Th2 cytokine environment related to infection susceptibility." (PMID 30510917, 2018). "Additionally, we assessed which T cells were more responsive to the infection, the Ag85-specific or the non-specific CD4+ T cells." (PMID 29499041, 2018). "In response to infection, CD4+ T cell-specific Stat3−/− mice have increased HSV-1-specific CD8+ T cells that express lower levels of KLRG-1 and IFNγ, suggesting that antiviral CD8+ T cell function relies in part on their cooperation with STAT3-competent CD4+ cells." (PMID 30167845, 2018). "CXCR4 is expressed on the majority of CD4+ T cells; however, CXCR4-tropic HIV-1 variants account for only a fraction of viruses worldwide and almost none that are involved in transmission and early infection." (PMID 29970186, 2018). "The ability of B cells to efficiently present several structural proteins from incoming virions to CD4+ T cells suggests that structural protein-specific CD4+ T cells are likely to play a more dominant role than CD8+ T cells during the very early stages of infection." (PMID 30521644, 2018). "Hence, it is not surprising to observe changes related to CD4+ T cell memory subsets in Ss infection." (PMID 29795573, 2018). "At 6 days post-infection, when the L4 stage had almost completely attenuated the clinical severity and pathological signs of EAE, CD25+ cell numbers expanded significantly, with parallel growth of CD8+ and CD4+, both CD25+Foxp3+ and CD25+Foxp3− subsets and alternatively activated macrophages." (PMID 28975357, 2018). "Testing four sgRNAs per gene targeting either CD4 or CD90, two surface markers whose expression could be easily assessed by flow cytometry, we observed that within 72 h after infection, between 20% and 40% of GFP+ T cells completely lost surface expression of CD4 or CD90, respectively." (PMID 29436394, 2018). "Interestingly Tscm cells were diminished in both CD4 and CD8 T cells and thus, the potential to repopulate other subsets of memory cells may be compromised in ECs at early stages of infection." (PMID 29490663, 2018). "The proportion of CD4 T cells secreting TNF-α or IFN-γ and CD8 T cells producing IFN-γ were further elevated in infected IL-10 KO splenocytes (p < 0.001), indicating that expression of IL-10 during naive T cell priming upon infection suppresses the generation of T cell responses." (PMID 30233599, 2018). "Therefore, a reduction in the influx of CD4+Foxp3+ cells at 30 days of infection does not play an evident role in controlling pathogen replication or the lung inflammatory response." (PMID 30584243, 2018). "M1- and M2-Mφ loaded with UV-TB40E as well as actively infected by TB40E induced comparable CD4+ T-cell proliferative responses, thus indicating that MHC class II dependent presentation of exogenous viral antigen to CD4+ T cells is constitutively high in Mφ and is not enhanced by active infection." (PMID 29887865, 2018). "Moreover, this provides a potential explanation for how AHR activation during development affects the ability of DCs to activate naïve CD8+, but not CD4+ T cells, following infection." (PMID 30412605, 2018).
infection (continued). "While it is now acknowledged that CD4+ T cells expressing CD25 and Foxp3 (Treg cells) regulate immune responses and, consequently, influence the pathogenesis of infectious diseases, the regulatory response mediated by Treg cells upon infection by Trypanosoma cruzi was still poorly characterized." (PMID 30455700, 2018). "However, the inefficient infection of CD4+ T cells and the absence of significant viremia during the early peak of EcoHIV infection indicate additional constraints of HIV infection of mice." (PMID 29879225, 2018). "The proportional increase in MAIT cells was significantly higher than that of CD4+ or CD8+ cells early during infection at day 5 post-infection (P < 0.001), though not by day 7 at which point antigen-specific responses will become dominant over other innate-like cells." (PMID 30413689, 2018). "However, depletion of CD4+ T cells in SIV-infected macaques leads to increased viremia due to a massive infection of macrophages, microglia, and possibly other cell types, indicating that CD4+ T cells are not necessarily required for SIV proliferation." (PMID 29309550, 2018). "In our study, IFN-γ production and CD4+ memory T cell expansion were observed in spleen and lung cells isolated from mice treated with HSP70 and GrpE at various time points after infection with Mtb K, indicating that both antigens are recognised by the host immune system as immunogenic antigens." (PMID 30258084, 2018). "Since BACH2 influenced effector CD4+ T cell subset development in vitro, and in particular the development of Tr1 cells, we hypothesized that BACH2 would influence cellular responses during infection, and consequently, affect disease outcome." (PMID 30459773, 2018). "Thus, we found that SIVcpz infection of hu-BLT mice does not result in a significant decrease of CD4+ T cells despite high viremia." (PMID 29615603, 2018). "We hypothesize that infection does not generate sufficient Ag85 protein levels to stimulate all P25 CD4+ T cells to their full potential." (PMID 29499041, 2018). "At the 14th day post-infection, there was a decrease switch in the number of CD4+ IL-10+T+ cells observed in WT and ST2−/− mice with an increase in ST2−/− mice and it lined up with the IL-10 amounts in infected joints at all times points evaluated (7–28 days post-infection)." (PMID 29867945, 2018). "However, the anatomic distribution and persistence of these diverse antigen-bearing APC are not known at this time, nor their options for encounter with lung-infiltrating CD4 T cells after primary infection." (PMID 29681900, 2018). "However, despite possible errors, transforming CD4 counts into a quantified estimation of the duration of the undiagnosed infection is not trivial because it frames the problem in a more meaningful way." (PMID 29933374, 2018). "Infection of CD4+ iNKT cells in humans and non-human primates leads to decline of CD4+ T cells." (PMID 30559739, 2018). "As a result, it is not unreasonable to expect that immunization or infection of old mice might elicit reduced CD4+ T cell responses." (PMID 29864157, 2018). "Results showed that consistent with our in vitro blocking results, in vivo blocking with α-CD200 antibodies resulted in a significant reduction of IL-10 levels in LdWT infection (CD200R+ panel, p = 0.0065), suggesting that blocking CD200 signaling could alter the CD4+ T cell characteristics." (PMID 29915577, 2018). "However, in contrast to Cd4-cre−Cd2apF/F mice, Cd4-cre+Cin85F/F mice were unable to control chronic LCMV infection with significantly higher viral burden in the peripheral blood at days 45 and 60 after infection compared to cre− littermate controls." (PMID 29734372, 2018). "On day four post infection viral loads in the tissues of the depleted and control mice were not significantly different, suggesting the innate immune response was not impacted by the absence of CD4+T cells in our animal model." (PMID 30212537, 2018).
infection (continued). "Additionally, a study of SUDV survivors, 12 years post infection, demonstrated strong memory CD4+, but not CD8+, T cell activation and neutralizing humoral immunity." (PMID 29795572, 2018). "In addition, CD4+ T resident memory cells (TRM) have been identified at sites distant from the primary lesion in L. major immune mice and increase the ability of circulating effector cells to mediate protection against the infection." (PMID 29867798, 2018). "We did however observe a site-specific reduction in the numbers of pMHC-specific CD4+ T cells in the draining lymph nodes and brains of old mice, compared with adults, after infection with West Nile virus and these differences were not impacted by the depletion of Tregs." (PMID 29864157, 2018). "The CD4 and CD8 T cell IFN-γ response to H1N1pdm09, the infecting strain, increased in peripheral blood after challenge, peaking 14d post-infection, then declined, reaching levels no longer significantly different from mock infected animals by 36d to 42d post-infection." (PMID 29666412, 2018). "However, microglia explanted during EAE, TMEV as well as JHMV infections failed to support myelin-specific CD4 T cell responses ex vivo, despite detection of internalized myelin." (PMID 29942315, 2018). "Our study provides clear evidence in humans that a CD4+IFN-γ response may be an immune correlate of protection against CT reinfection and adds substantial evidence to existing knowledge of the human immune responses in CT-infection." (PMID 30245688, 2018). "Interestingly, the higher level of CD4+ T cell activation in AHIs was correlated with less decline of CD4+ T cell count after 2 years of infection without ART (r = −0.46, p = 0.01)." (PMID 29636753, 2018). "This modulation of glucose metabolism in HIV-1 infected CD4+ cells, and their increased sensitivity to metabolic inhibition, are consistent with viral dependency on metabolic resources of the host, though a cellular response to infection cannot be ruled out." (PMID 29518929, 2018). "Another study by the same group could not measure a significant difference between the infection frequencies in memory CD4+ cells from lymph nodes and peripheral blood in untreated HIV-infected individuals, although there was a trend to higher infection levels in tissue." (PMID 29378657, 2018). "Although antigen-specific CD4+ T cells have been shown to be the major producer of IFN-γ, recent results suggest that other subsets of immune cells including NK cell, NKT cell, and CD8 T cells also contribute to the secretions of IFN-γ, in particular, at the early stage of infections." (PMID 28936213, 2017). "IFN-γ could limit the infection of MTB, while IL17 could induce IFN-γ secretion by CD4+ T cells." (PMID 29196714, 2017). "In summary, among highly exposed children, all of whom had a measurable Pf-specific CD4 T-cell response, neither the frequency of these cells nor their cytokine production profiles correlated with prospective protection from infection after adjustment for household exposure intensity." (PMID 29097996, 2017). "However, CD4+ T cells are not equally permissive to infection, varying between individuals and across cells isolated from the same individual." (PMID 29073251, 2017). "However, later during infection, memory CD4+ T cell proliferation was curtailed and no protection was observed." (PMID 29176787, 2017). "Using this novel assay that measures transcriptionally competent HIV-infected cells, we found that after ex vivo infection of unstimulated PBMCs, HIV transcription was significantly detected in T cells and production of viral proteins correlated well with the downregulation of the CD4 cell receptor." (PMID 28698276, 2017). "As expected, the median CD4 cell count was higher in those with a recent infection confirmed by a RITA assay: 546 cells/μL (1098 individuals) compared with 305 cells/μL (4864 individuals) in nonrecent infections." (PMID 27476929, 2017).